KRAS (KRas proto-oncogene, GTPase)
Diseases named in the same sentence as KRAS in open-access papers (continued):
Sharing a sentence is not in itself a finding about the gene and the disease.
tumor (continued). "To gain insights into the mechanism by which PTPN2 regulates the proliferation and survival of KRAS-dependent tumor cells, we first checked whether PTPN2 affects the KRAS activation, using an RAS-GTP pulldown assay." (PMID 33122197, 2020). "Taken together, these experiments suggest that the lack of Id1 expression in both tumor cells and the tumor microenvironment, along with the blockade of PD-1/PD-L1 axis, exerts the most potent antitumor effect in murine KRAS-driven LUAD." (PMID 33126649, 2020). "In the tumor tissues of H2228 cells-engrafted mice, the expression level of wild-type KRAS protein was not significantly changed in both the AdV-Cas9 or AdV-Cas9-sgG12S treated groups." (PMID 32308773, 2020). "Also, PFS and OS were significantly shorter in patients with KRAS/STK11 co-mutant tumor than in those with KRAS mutant and STK11 wild type (KRASm/STK11wt) tumor (PFS: p < 0.001; OS: p = 0.0015)." (PMID 32365882, 2020). "In 37 of 136 (27.2%) analyzed KRAS non-amplified tumor samples KRAS protein expression was observed." (PMID 32571252, 2020). "It is interesting to note that while KRAS and EMT pathways that result in aggressive tumor biology are enriched in the GR-high group, immune pathways IL2 and apoptosis are also enriched, which may play a role in influencing overall survival." (PMID 32629782, 2020). "The resulting topology integrates centrally involved proteins of the common signaling pathways and generally accepted cancer drivers in CRC—such as APC, p53m, KRAS, DCC, TGFβR, PTEN and SMAD4 allowing a simplified view on the progression from normal cells to tumor cells (Table A2, Figure A8)." (PMID 31861874, 2019). "There have been studies reporting that the interaction between KRAS and YAP1 could regulate EMT and tumor survival." (PMID 31827075, 2019). "In our study, multiple testing over time enabled the evaluation of association between the presence of KRAS-mutated ctDNA and prognosis of PDAC irrespective of tumor resection." (PMID 31891652, 2019). "In conclusion, due to the high level of phosphorylation of YB-1 in tumor tissues from CRC patients, cotargeting YB-1 and Akt is a suitable approach to reduce cell proliferation in CRC cells, independent of KRAS mutational status." (PMID 31010234, 2019). "Recent studies have shown that PDA tumor cells can survive in the absence of oncogenic KRAS (referred to hereafter as KRAS*) signaling by activating alternative mechanisms that maintain their growth." (PMID 31134896, 2019). "Multivariate analysis revealed that detection of KRAS ctDNA was the only independent prognostic factor regardless of tumor resection (hazard ratios = 54.5 for patients who underwent surgery and 10.1 for patients who did not undergo surgery; P<0.001 for both)." (PMID 31891652, 2019). "Activated KRAS are the only RAS type that could induce growth inhibition and apoptosis, indicating that mutant KRAS has both tumour-promoting and -suppressing functions." (PMID 30833665, 2019). "There was no detectable tumor in the negative control (KRAS+/−Apcf/f) even after 180 days (video clips attached)." (PMID 31766149, 2019).
tumor (continued). "To confirm this finding, we repeated the IRE + anti-PD1 treatment in additional 7 KRAS*-bearing mice: 3 of these 7 mice (43%) reached the 60-day study endpoint with no palpable tumor." (PMID 30796212, 2019). "The observed gradient formed regardless of oncogenic activation of the upstream KRAS GTPase, and in the absence of tumour stroma that is not present in the organoids." (PMID 31266962, 2019). "Indeed, KRAS and NRAS mutant tumours and to a lesser extent BRAF mutant tumours are highly sensitive to combinations of PARP with MEK/ERK inhibitors in vitro, whereas for KRAS mutant models this evidence is available in vivo." (PMID 31374917, 2019). "In contrast, KRAS and NRAS mutations have not been detected in tumour biopsy from patients that progressed following treatment with first-generation TKIs." (PMID 30857358, 2019). "Although enhancing RAS-ERK signaling during normal tumor growth conditions, NF1 deficiencies are not as dominant drivers of MAPK signaling activity as oncogenic versions of KRAS." (PMID 30858928, 2019). "Furthermore, we analyzed the MAF of KRAS in PC, and revealed for the first time that the KRAS MAF in ctDNA was significantly different from that in matched tumor tissue." (PMID 31850201, 2019). "The mutant KRAS ctDNA was found to be related with the clinical stage of PC patients, whereas KRAS MAF in tumor tissue was not." (PMID 31850201, 2019). "Abnormal proliferative signals of oncogenic insults including oncogenic KRAS are known to activate a senescent phenotype in cells, presumably designed to prevent the growth of oncogene-transformed cells and to preserve the tumor in a non-aggressive state." (PMID 31041783, 2019). "Vitamin C treatment selectively kills mutant KRAS expressing tumor cells, but not wild-type KRAS containing cells." (PMID 30971271, 2019). "In KRAS-mutant mouse tumors, immune suppression may be a result of MYC co-activation leading to the recruitment of proangiogenic macrophages in the tumor microenvironment." (PMID 31775797, 2019). "Relapsed tumors retain KRAS* pathway suppression and a subset harbor genomic amplification of the Hippo pathway transcriptional coactivator, YAP1, which we have confirmed in 3 of 7 ‘Escaper’ tumor cells lines (cell lines denoted as EY1-3)." (PMID 31134896, 2019). "Analysis of the TME of mutant KRAS tumors and the study of the molecular mechanisms involved in the crosstalk between mutant KRAS cancer cells and the TME has provided valuable information on the regulation of tumor initiation and progression." (PMID 31847096, 2019). "Moreover, in vivo delivery of miR-873 nanoparticles inhibited KRAS expression and tumor growth in PDAC and TNBC tumor models." (PMID 30654191, 2019). "Furthermore, our results showed a clear correlation of PDE6D expression and cellular localization with tumor grading, tumor stages, ERK activation, and KRAS activation." (PMID 30901922, 2019). "Other groups have also had some early success targeting KRAS in PDAC and CRC tumor models." (PMID 31413817, 2019). "In our case, next-generation sequencing technology detected KRAS G12C and CTNNB1 G34R mutations, absence of microsatellite instability and low tumor mutation burden (three mutations per megabase)." (PMID 31266530, 2019). "Moreover, in the KRAS*-bearing mice that survived for 60 days after the initiation of IRE + anti-PD1 treatment, all rejected tumor cell re-challenge, along with an anti-tumor memory T cell response." (PMID 30796212, 2019). "The fact that the original tumor was EGFR and KRAS wt classified it for second line EGFR treatment." (PMID 31323891, 2019). "In this study, the oncogenic impact of four non-canonical/novel KRAS and NRAS mutations identified from malignant CRC tumor samples were investigated." (PMID 31816869, 2019). "KRAS can also mediate activation of canonical Wnt signaling while suppressing non-canonical Wnt pathways to promote tumor growth." (PMID 31681559, 2019).
tumor (continued). "As we did not perform microdissection of tumour subregions, we cannot comment on KRAS status heterogeneity within the same tumour." (PMID 31111275, 2019). "In KRAS-mediated lung tumors, the depletion of Atg5 or Atg7, two mitophagic effectors involved in LC3/GABARAP lipidation, has induced a reduction in tumor burden and an increase in survival compared to the counterpart even if malignancies present a faster tumor-initiation stage." (PMID 31210843, 2019). "Moreover, TEAD induced cytokines IL-6 and CSF1-3 in KRAS mutant PDAC cells to recruit myeloid-derived suppressor cells (MDSCs), which formed an immunosuppressive tumor microenvironment." (PMID 31212916, 2019). "Further stratification using molecular markers, such as BRAF and KRAS mutations, and MSI status have been investigated with regard to their prognostic potential in this tumour group, but have not widely adopted to direct clinical management." (PMID 31775679, 2019). "This implies that in response to nutrient stress, oncogenic KRAS could likewise activate downstream NRF2 and ATF4-dependent antioxidant mechanisms to support tumor progression." (PMID 31852884, 2019). "Validation with RNA-seq data of blood platelets shows that DDR achieves the superior performance in classification of six different tumor types as well as molecular target statuses (such as MET or HER2-positive, and mutant KRAS, EGFR or PIK3CA) with smaller sets of biomarkers." (PMID 31752658, 2019). "For example, KRAS induces the phosphorylation of the Frizzled co-receptor LRP6, leading to a cascade of events that promotes activation of the WNT pathway and increases in cell migration and tumor growth." (PMID 31623618, 2019). "We selected a KRAS and APC mutant organoid line which responded to MEK inhibition with a strong increase in Wnt activity and could establish viable tumours with a take rate of 100%." (PMID 31097693, 2019). "It is thus plausible that expression programs we underscored in the Gprc5a−/−Kras-mutant LUAD CSCs may be conserved, at least in part, in human KRAS-mutant LUAD; particularly programs influencing stemness, pro-tumor inflammation and antioxidant function." (PMID 31001473, 2019). "The tumor was EGFR+ in a group of 24 patients and KRAS+ in another set of 24 subjects." (PMID 30999636, 2019). "KRAS expression analysis of tumor samples after TPN treatments (non-targeting, TPN-siKRAS and dual treatment TPN-siKRAS+TPN-21) was performed by Western blot and we found." (PMID 31523393, 2019). "In patients with treatment benefit (n = 21), no mutations in KRAS, NRAS, and BRAF were detected in tumor tissue." (PMID 31350822, 2019). "It has previously been shown that afatinib can suppress tumor growth in KRAS-mutant NSCLCs, but not erlotinib or gefitinib." (PMID 30935067, 2019). "Recently, considerable literature have demonstrated that a KRAS regulated non-canonical Gln metabolism pathway that enables proliferation and tumor growth in PDAC cell lines." (PMID 31470862, 2019). "Using a next-generation sequencing assay, we documented genomic alterations in KRAS and CTNNB1, low tumor mutation burden (TMB), and an absence of microsatellite instability." (PMID 31266530, 2019). "The AJCC‐UICC have included other prognostic factors such as degree of differentiation, R classification, circumferential resection margin, tumor regression score, CEA level, lymphovascular invasion, perineural invasion, microsatellite instability, KRAS, NRAS, and BRAF." (PMID 31069966, 2019). "Thus, PKCι-PAK1 signaling is an important pathway in tumor genesis in EGFR mutant, KRAS mutant and SCC cell lines." (PMID 31660987, 2019).
tumor (continued). "However, it is now clear that KRAS-mutant NSCLC is a heterogeneous disease, including different tumour subtypes with variable biological background, different prognosis and clinical response to immunotherapy." (PMID 30377342, 2019). "For patients with mCRC, KRAS, NRAS and BRAF tumour genotyping has therefore a major impact on clinical management and genotyping results should be available within 7 working days to ensure a rational first-line treatment selection based on validated molecular data." (PMID 31265477, 2019). "Given that the combination of IRE + anti-PD-1 was able to increase the intratumoral frequency of CD8+ T cells, we next studied to what extent IRE modulated the stroma of KRAS* tumors; because it is known that modulation of PDAC stroma enhances tumor infiltration of CD8+ cells." (PMID 30796212, 2019). "The chemotherapy-resistant cancer cells and the KRAS mutants were also eliminated due to a tumor microenvironment that was non-immunosuppressive, non-angiogenic and that contained no pro-tumor cells at the start of the treatment." (PMID 35847834, 2018). "Having found that MHYs inhibited the tumor growth only in Caco2 and HT29 cells, it is possible that the KRAS status is correlated with resistance to MHYs and in other words, MHYs require wild type KRAS to exert their anti-cancer effects." (PMID 30158525, 2018). "Compared with control NT siRNA, knockdown of KRas in MiaPaCa2, but not in A549, cells inhibited tumor growth in mice, confirming in vivo the dependency of MiaPaCa2 but not A549 tumors on KRas." (PMID 30514931, 2018). "Of note, bona-fide mutant KRAS-specific T cells have been primarily identified in situ, i.e., in the tumor lesion, and not in the peripheral circulation." (PMID 30283732, 2018). "By reviewing the list of genes without impact like ERBB3, CASP8, RAF1 and KRAS (FaDu) as well as KEAP1, KRAS, RAF1 and FANCD2 (SAS), one finds tumor drivers ranked among the top 100 mutated genes in HNSCC." (PMID 29719593, 2018). "Although most FAP neoplasms develop without requiring aberrant methylation, some FAP neoplasms develop in the presence of both IME and KRAS mutations, demonstrating aberrant methylation and oncogene mutations." (PMID 30220972, 2018). "Taken together, the cross-talk between miR-532-5p, KRAS, NAP1L1, and EST1 established a bridge between miR-532-5p and the MAPK-signalling pathway, demonstrating that miRNAs and their target genes participate in the development and progression of tumours." (PMID 30082686, 2018). "In 18 samples with less than 32% viable tumor cells, we detected no mutations, but we found KRAS and EGFR mutations in 10 of 80 (13%) patient samples with 32% or more viable tumor cells." (PMID 29673125, 2018). "Regardless of the KRAS status in tumor tissues, patients with MctDNA in blood showed poor PFS with first-line treatment." (PMID 29849949, 2018). "KRAS exons 2-4 (KRAS2-4), NRAS2-4, BRAF15 were evaluated in 67 tumours by ION Torrent platform." (PMID 29899858, 2018). "In an exploratory analysis, data on KRAS status in ctDNA were combined with previously obtained data on KRAS/NRAS status in tumour tissue and patient outcome assessed by presence/absence of these mutations." (PMID 29362371, 2018). "NGS analysis of the two tumors showed an amplification of MYC with a copy number of 76 in the 2017 tumor, which was not present in the 2011 tumor, along with a significant mutant KRAS amplification." (PMID 30788462, 2018). "In tumor cells, Nrf2 is usually activated by ROS-induced oncogenes, such as KRAS and c-MYC, and inhibition of its activity may contribute to the apoptosis of tumor cells and abrogated tumor growth." (PMID 30538633, 2018).
tumor (continued). "Samples with either TRPV4, KRAS, or FGFR1 mutations had strong phospho-ERK staining in a large component of the mononuclear cells in the tumor, while the multinucleated giant cells were negative, as expected." (PMID 30385747, 2018). "Importantly, IL-1β-mediated NF-κB induction in KRAS-mutant tumor cells, as well as their resulting MPE-competence, can only be blocked by co-inhibition of both KRAS and IKKα, a strategy that overcomes drug resistance to individual treatments." (PMID 29445180, 2018). "Considering the results that wild-type H and NRAS is required for the mutant KRAS-induced tumor progression, degradation of wild-type H and NRAS together with the mutant KRAS provide a benefit for the application of KYA1797K and derivatives as anti-cancer drug candidates." (PMID 29872723, 2018). "This conclusion was supported by various lines of evidence: (i) loss of GATA2 reduced the viability of Ras-mutated NSCLCs, but not of WT NSCLCs; (ii) in KRAS-driven NSCLC mouse model, GATA2 loss strongly reduced tumor development." (PMID 30060526, 2018). "As for the mutational status of the KRAS, NRAS and BRAF genes, no discordance was observed between the primary tumours and the metastases." (PMID 30029640, 2018). "Indeed, increased expression of a ‘KRAS signaling’ gene signature was detected in both JNKWT and JNKKO tumor cells." (PMID 29856313, 2018). "Epidermal growth factor receptor (EGFR) mutations enable constitutive active downstream signaling of PI3K/AKT, KRAS/ERK and JAK/STAT pathways, and promote tumor progression by inducing uncontrolled proliferation, evasion of apoptosis and migration of non-small cell lung cancer (NSCLC)." (PMID 29455644, 2018). "This is also reflected by studies detecting mutant KRAS in free circulating DNA in cancer-free subjects, indicating that the activation of KRAS is not a specific indicator of malignancy and not suitable as an isolated biomarker for tumor detection." (PMID 30564197, 2018). "Here, we determine that non-canonical IKKα-RelB pathway activation of KRAS-mutant tumor cells mediates MPE development and this is fueled by host-provided interleukin IL-1β." (PMID 29445180, 2018). "In patient P2, ROS1 p.I1967V levels in plasma DNA dramatically decreased after a surgical operation, which is indicative of tumor removal; however, this was not reflected in the MP/KRAS and MP/FNA." (PMID 30072705, 2018). "Erastin is another anti-tumor agent that use VDAC as a docking site in mitochondria and induces oxidative, non-apoptotic death in human tumor cells with mutations in the oncogenes HRAS, KRAS, or BRAF." (PMID 29682501, 2018). "In addition, our results demonstrate that miR-422a functions as a tumor suppressor by directly targeting BCL2L2 and KRAS." (PMID 29358307, 2018). "We, therefore, tested the antigen specificity of PDAC-infiltrating B cells (TIB) by first isolating them from tumor tissue, immortalizing them using Epstein-Barr virus (EBV) infection and assessing their IgG production against wild type and mutant KRAS targets." (PMID 30283732, 2018). "These genetic alterations involving BRAF, KRAS, RAF1, NF1, FGFR1, and FGFR2 were mutually exclusive (i.e. no tumor harbored any two of these variants simultaneously)." (PMID 29880043, 2018). "Meanwhile, KRAS, NRAS and BRAF are potential tumor-driven genes themselves." (PMID 30416987, 2018).